SRCAP (Snf2 related CREBBP activator protein)
Description:
Acts both as a chromatin remodeler and transcription coregulator. Catalytic component of the SRCAP complex which mediates the ATP-dependent exchange of histone H2AZ/H2B dimers for nucleosomal H2A/H2B, leading to transcriptional regulation of selected genes expression through chromatin remodeling. Acts as a coactivator for CREB-mediated transcription, steroid receptor-mediated transcription, and Notch-mediated transcription.
Synonyms: KIAA0309; SWR1; DOMO1; DEHMBA; FLHS
Tractability: Small molecule: a structure with a bound ligand is known. PROTAC: ubiquitination databases record sites on it; its protein half-life has been measured.
Gene: Protein-coding gene on chromosome 16 (30,698,166 to 30,741,409, forward strand). Ensembl gene ENSG00000080603.
Subcellular location: Nucleus
Subcellular location (Human Protein Atlas): Nucleoplasm; Golgi apparatus; Nuclear bodies
Gene Ontology:
Molecular function: ATP hydrolysis activity; ATP-dependent chromatin remodeler activity; transcription coactivator activity; ATP binding; DNA binding
Biological process: cAMP/PKA signal transduction; positive regulation of transcription by RNA polymerase II; chromatin remodeling; regulation of DNA-templated transcription; regulation of gene expression
Cellular component: nuclear body; nucleoplasm; nucleus; perinuclear region of cytoplasm; protein-containing complex; Swr1 complex; nucleosome; catalytic complex; chromatin
Genetic constraint (gnomAD): Loss-of-function variants: 46 observed, 263.37 expected, observed/expected ratio (o/e) 0.17, 90% interval 0.14 to 0.22. The upper end of that interval is the gene's LOEUF score, 0.22, which puts it in group 1 of 6, group 1 being the genes least tolerant of losing a copy. Missense variants: 3,649 observed, 4,304.3 expected, observed/expected ratio (o/e) 0.85, 90% interval 0.82 to 0.87. Synonymous variants: 1,798 observed, 1,731 expected, observed/expected ratio (o/e) 1.04, 90% interval 1 to 1.08.
Gene-disease validity (ClinGen):
ClinGen rates the evidence that SRCAP causes each of these diseases.
Floating-Harbor syndrome (autosomal dominant): Definitive. Floating-Harbor syndrome is a genetic developmental disorder characterized by facial dysmorphism, short stature with delayed bone age, and expressive language delay.
Homologues: Orthologues: chimpanzee SRCAP (99% identical), macaque SRCAP (98% identical), dog SRCAP (93% identical), pig SRCAP (92% identical), rabbit SRCAP (91% identical), guinea pig SRCAP (88% identical), rat Srcap (88% identical), mouse Srcap (87% identical), tropical clawed frog SRCAP (46% identical), zebrafish srcap (40% identical). Paralogues in human: EP400 (22% identical), CHD2 (11% identical), INO80 (11% identical), CHD1 (11% identical), CHD9 (11% identical), SMARCA4 (11% identical), SMARCA2 (11% identical), CHD7 (11% identical), CHD3 (10% identical), CHD5 (10% identical), CHD6 (10% identical), CHD8 (9% identical), and 18 more.
Diseases named in the same sentence as SRCAP in open-access papers:
SRCAP is named in the same sentence as 74 diseases in open-access papers, as found by Europe PMC text mining. Sharing a sentence is not in itself a finding about the gene and the disease. The quoted sentences say what the papers report.
Floating-Harbor syndrome (31 papers, 2013 to 2026). "While SRCAP mutations have been previously connected to the pathogenesis of Floating-Harbor syndrome (FHS), these typically occur downstream, with a hotspot mutation leading to protein truncation after amino acid 2444." (PMID 40858549, 2025). "SRCAP encodes an ATPase and is linked to developmental delays and Floating-Harbor syndrome (FHS) when this gene loses function, FHS is a rare genetic disease typically manifesting in early childhood, characterized by short stature and facial dysmorphism." (PMID 38764094, 2024). "Mutations in a human homolog of SWR1C, SRCAP is implicated in Floating Harbor syndrome, which results in skeletal and facial defects." (PMID 38809771, 2024). "Variants of SRCAP have been identified in patients presenting with neurodevelopmental disorders (NDDs), and their relations with Floating-Harbor syndrome (FLHS; OMIM #136140) are particularly well defined." (PMID 36814905, 2023). "Floating-Harbor syndrome is a rare genetic disease affecting human development caused by dominant truncating mutations in the SRCAP gene, which encodes the ATPase SRCAP, the core catalytic subunit of the homonymous chromatin-remodeling complex." (PMID 34474679, 2021). "Patient 7 showed a frameshift variant, p.(Pro2459Leufs*16), in SRCAP, which is the causative gene for Floating-Harbor syndrome." (PMID 32546215, 2020). "The clinical picture was highly suggestive of the Floating-Harbor syndrome, Sanger sequencing/exon sequencing of exon 34 of the SRCAP gene, disclosed a de novo truncating mutation (c.7371delT), likely pathogenic." (PMID 32928283, 2020). "Heterozygous mutations in SRCAP have been extensively linked to Floating-Harbor syndrome, which is characterized by low birth weight, short stature, skeletal anomalies, and intellectual disability." (PMID 25299611, 2014). "We have assembled the largest cohort of individuals with Floating-Harbor syndrome; documenting pathogenic mutations in SRCAP in 52 affected individuals." (PMID 23621943, 2013). "Examples of reclassification of VUS in our study include a novel and distinctive phenotype for the SRCAP gene, previously associated with Floating-Harbor syndrome only, a VUS in PRPS1 recently also reported by others, and small genotype-phenotype case series for LMBRD2 and PAX3." (PMID 35710456, 2022). "Floating-Harbor syndrome (FLHS) is a rare neurodevelopmental and skeletal disorder caused by truncating variants in exons 33 and 34 of the SRCAP gene." (PMID 42095020, 2026). "Truncating variants in the last two exons (exons 33 and 34) of the SRCAP cause the neurodevelopmental disorder Floating-Harbor syndrome (FLHS)." (PMID 41282476, 2025). "Moreover, our findings emphasize a surprising scenario whereby alterations in cell division produced by SRCAP mutations may contribute to the onset of Floating-Harbor syndrome." (PMID 34474679, 2021). "Another example is Floating-Harbor syndrome (FHS), a rare autosomal dominant due to mutations in the SRCAP gene that can also result in short stature." (PMID 32935225, 2020). "In another study, we established a DNA methylation signature specific to individuals with Floating Harbor syndrome [FLHS; MIM:136140] caused by pathogenic variants in exons 33/34 of the SRCAP [MIM:611421] gene." (PMID 37022461, 2024). "Other examples of genes with multiple signatures are SRCAP (Floating Harbor syndrome and DEHMBA), KMT2D (Kabuki syndrome and CHARGE-like phenotype) and KAT6B (GTPTS and SBBYSS)." (PMID 35860466, 2022). "According to the canonical role played by the SRCAP protein in epigenetic regulation, the Floating-Harbor syndrome is thought to be a consequence of chromatin perturbations." (PMID 34474679, 2021). "Interestingly, a recent study showed that a S38T substitution in H2A.Z.1, mimicking T38 found in H2A.Z.2, rescues the SRCAP-dependent Floating-Harbor Syndrome." (PMID 32109204, 2020).
Floating-Harbor syndrome (continued). "Components of the SRCAP complex are upregulated in several tumors, such as ovarian tumors, breast tumors, thyroid tumors, prostate tumors, melanoma, bladder tumors, glioma, and Floating-Harbor syndrome (FHS)." (PMID 37958827, 2023). "The absence of the C-terminal AT-hook structure in SRCAP is the main cause of Floating-Harbor syndrome (FHS)." (PMID 35152838, 2022). "Parents 3, 4 and 6 are the parents of individuals who were enrolled with a clinical diagnosis of Floating Harbor syndrome (FHS), and for whom targeted sequencing of the newly identified SRCAP gene confirmed this diagnosis molecularly." (PMID 27082877, 2016).
prostate carcinoma (4 papers, 2014 to 2023). A carcinoma that arises from epithelial cells of the prostate gland. "Their homologs are significantly mutated (SRCAP in prostate cancer and glioblastoma; CLASPIN in gliomas and breast cancer) or overexpressed (H2A.Z in liver, colorectal, and metastatic breast cancer) in human cancers, and these alterations are predicted to play important roles in carcinogenesis." (PMID 30206225, 2018). "The chromatin remodeling factor SRCAP regulates prostate-specific antigen expression and cellular proliferation in prostate cancer cells." (PMID 36741260, 2023). "As a co-activator for the androgen receptor (AR), SRCAP promotes the proliferation and mediates the expression of prostate-specific antigen in prostate cancer." (PMID 35152838, 2022). "In human tumors, SRCAP has only been reported in prostate cancer." (PMID 35152838, 2022). "Furthermore, inhibition of SRCAP expression has been shown to interfere with the androgen-dependent stages of prostate cancer cell growth." (PMID 24398858, 2014). "Indeed, an AR responsiveness persists in the androgen-dependent to -independent transition of prostate cancer and, with its co-activator SRCAP, AR could potentially bring the over-expressed H2A.Z.1 to different promoters." (PMID 24398858, 2014). "One such co-activator is SNF2-related CBP activator protein (SRCAP) that catalyzes the ATP-dependent incorporation of H2A.Z–H2B heterodimers into chromatin and whose deregulation plays a critical role in prostate cancer." (PMID 24398858, 2014).
breast carcinoma (3 papers, 2018 to 2025). "This loss of SRCAP inhibition results in proliferation and invasion of breast cancer cells, suggesting its role as an oncogene." (PMID 41278204, 2025). "This suggests that the regulation of p400/Tip60 and SRCAP complexes is related to breast cancer progression, but their exact function needs further exploration." (PMID 41278204, 2025). "From the result of Western blot, SRCAP was up-regulated in breast cancer tissues compared with the normal tissues (p < 0.01)." (PMID 35152838, 2022). "The expression correlation of LINC00665/miR-641/SRCAP was verified in clinical samples of breast cancer patients." (PMID 35152838, 2022). "We demonstrate that LINC00665 is overexpressed in breast cancer, and up regulated the expression of SRCAP through sponging miR-641 to finally promote the survival and metastasis of breast cancer cells." (PMID 35152838, 2022). "In conclusion, LINC00665 could promote the survival and metastasis of breast cancer cells through sponging miR-641 and targeting SRCAP." (PMID 35152838, 2022). "To further verify our hypothesis, we detected the expression levels of LINC00665, miR-641, and SRCAP in clinical samples from 10 breast cancer patients." (PMID 35152838, 2022). "In the present research, we investigated the effect and molecular mechanism of LINC00665 as a ceRNA in breast cancer cells, and confirmed that LINC00665/miR-641/SRCAP axis regulates tumor cell survival and metastasis through EMT and AKT pathway." (PMID 35152838, 2022).
Uterine leiomyoma (3 papers, 2023 to 2024). The presence of a leiomyoma of the uterus. "Other rare molecular driver aberrations occurring in uterine leiomyoma included somatic mutations in genes encoding six members of SRCAP histone-loading complex leading to H2A.Z loading defect." (PMID 37466765, 2024). "UK Biobank whole-exome data revealed an association between mutations in genes encoding the SRCAP complex and uterine leiomyomas (ULs)." (PMID 36773604, 2023). "Although this study links complex genetic mutations in SRCAP to the occurrence of uterine fibroids, further research is required to understand the molecular mechanisms involved." (PMID 37435030, 2023). "It has been proved that patients with germinal mutation in the SRCAP members YEATS4 and ZNHIT1 predispose to uterine leiomyoma." (PMID 37466765, 2024).
colorectal cancer (2 papers, 2023 to 2025). A primary or metastatic malignant neoplasm that affects the colon or rectum. "In the HMF colorectal cancers, we discovered eight predictive gene deficiency models (MSH3, SMC2, SMC6, BMPR2, CLASP2, SRCAP, UBR5, and UVRAG) of monoallelic LOF with PR-AUC-E ranging from 0.21 (CLASP2) to 0.62 (MSH3) (AUROC ranging from 0.68 for SRCAP deficiency to 0.94 for MSH3 deficiency)." (PMID 36883553, 2023). "To determine if SRCAP-1879 affects cell migration in other cancer types, we performed the migration assay using A-253 (salivary gland carcinoma), CAL 27 (tongue SCC), and HCT 116 (colorectal carcinoma) cells, and in every case, SRCAP-1879 significantly increased migration." (PMID 40858549, 2025).
leiomyoma (2 papers, 2022 to 2023). A well-circumscribed benign smooth muscle neoplasm characterized by the presence of spindle cells with cigar-shaped nuclei, interlacing fascicles, and a whorled pattern. "These tumors were also negative for MED12 and HMGA2 defects, as well as for mutations in genes encoding for proteins of the SRCAP complex, another recently discovered leiomyoma subtype." (PMID 36068196, 2022). "Aberrations in MED12, HMGA2, FH, and SRCAP complex genes account for most leiomyomas, but ~10% of leiomyomas do not harbor defects in any of these genes." (PMID 35822448, 2023).
viral infection (2 papers, 2024 to 2025). "Taken together, we postulate that SRCAP may promote viral infection by activating viral RNA transcription, although further study is needed to confirm the hypothesis." (PMID 39530666, 2024).
Alzheimer disease (1 paper, 2023). A progressive, neurodegenerative disease characterized by loss of function and death of nerve cells in several areas of the brain leading to loss of cognitive function such as memory and language. "Similarly, DNMT3B and SRCAP variants have also been linked to neurodegenerative disorders, including Alzheimer’s disease (AD), PD, and amyotrophic lateral sclerosis (ALS)." (PMID 36814905, 2023).
cognitive decline (1 paper, 2025). "SNPs in this region mapped to PRR14, SRCAP, and BCL7C—genes linked to brain function, neurodegeneration, and cognitive decline." (PMID 40332088, 2025).
colon cancer (1 paper, 2025). "This SRCAP-1879 hotspot truncation has previously been noted in a colon cancer DNA-sequencing study, although the functional significance of this mutation remained unclear." (PMID 40858549, 2025).
hearing loss (1 paper, 2023). "The SRCAP complex is part of the SWR subfamily, and truncating mutations in SRCAP result in Floating–Harbor syndrome (FHS), in which some cases are associated with hearing loss." (PMID 36831199, 2023).
keratinocyte carcinoma (1 paper, 2025). A skin cancer arising from the keratin-producing cells of the epidermis. "SRCAP is in the top 2% most frequently mutated genes in cSCC, which is the more aggressive of the two keratinocyte carcinomas." (PMID 40858549, 2025). "In this study, we first noted that SRCAP is frequently mutated in keratinocyte carcinomas." (PMID 40858549, 2025). "Further, SRCAP is most frequently mutated in keratinocyte carcinomas." (PMID 40858549, 2025).
Macrocephaly (1 paper, 2024). Occipitofrontal (head) circumference greater than 97th centile compared to appropriate, age matched, sex-matched normal standards. "In addition, two children in our sample, one with a mutation in PTPN11, and the other with mutations in TSC2 and SRCAP, also exhibited macrocephaly (a structural anomaly)." (PMID 39350038, 2024).
Rubinstein-Taybi syndrome (1 paper, 2014). A rare malformation syndrome characterized by congenital anomalies (microcephaly, specific facial characteristics, broad thumbs and halluces and postnatal growth retardation), short stature, intellectual disability and behavioral characteristics. "However, absence of SRCAP mutations were reported in 3/9 patients investigated by direct sequencing and may have different explanations, e.g. an overlapping phenotypic spectrum with Rubinstein-Taybi syndrome or other syndromes as well as possible genetic heterogeneity in FHS." (PMID 25433523, 2014).
cancer (13 papers, 2012 to 2025). A tumor composed of atypical neoplastic, often pleomorphic cells that invade other tissues. "Because relatively few cases of cSCC (176 patients) have been sequenced for mutations, we used pan-cancer data (>91,000 patients), which revealed that missense and truncating mutations occur across the length of SRCAP." (PMID 40858549, 2025). "Using data from cBioPortal, we identified SRCAP as a frequently mutated gene in cSCC and identified a mutational hotspot in SRCAP using pan-cancer data." (PMID 40858549, 2025). "In summary, the SRCAP-1879 truncation induces transcriptional changes in multiple cellular processes associated with cancer (proliferation, differentiation, motility, and EMT) in different cell states." (PMID 40858549, 2025). "Deficient H2A.Z disposition in uterine leiomyoma cells with SRCAP complex mutations suggests a cancer inhibition role." (PMID 39199381, 2024). "Using pan-cancer data, we identified the mutational hotspot in SRCAP at amino acid 1879." (PMID 40858549, 2025). "Finally, we wanted to compare the SRCAP-1879 cancer hotspot mutation to a known pathogenic SRCAP mutation." (PMID 40858549, 2025). "While the majority of studies have posited H2A.Z as a pro-carcinogenic factor, a recent study has revealed the deficient H2A.Z disposition in uterine leiomyoma cells with SRCAP complex mutations, which suggests a cancer inhibition role of H2A.Z in tumorigenesis." (PMID 39199381, 2024). "The majority of these Cfdp1 alterations are associated with uterine endometrial carcinomas, suggesting that Cfdp1, and likely the SRCAP remodeler, are key for suppressing cancer initiation or progression in this cell type." (PMID 38809771, 2024). "Our characterization of this hotspot mutation, leveraging primary human keratinocytes and the Ras-CDK4 cSCC model, demonstrates that the SRCAP-1879 truncation is sufficient to dysregulate gene expression in a cell-state-dependent manner and promote cancer invasion with the induction of MMP9." (PMID 40858549, 2025). "Considering the large size of the SRCAP protein, with a total of 3230 amino acids, it remains to be established whether other mutations than the ones involved in FHS can influence cancer progression." (PMID 40858549, 2025). "The cancer hotspot mutation altered gene expression without changing H2A.Z chromatin occupancy in the presence of wild-type SRCAP." (PMID 40858549, 2025). "Among the top most significant EMT-specific hits, one-third belonged to the category of histone methylation writers, whereas several ERGs (including KMT2A, EP400, MBD5, and SRCAP) were found to be frequently targeted by genetic alterations in several cancer types." (PMID 32963031, 2020). "Since the SRCAP-1879 truncation does not alter H2A.Z occupancy, it suggests that the pro-cancer effects of the cancer hotspot mutation may be H2A.Z independent." (PMID 40858549, 2025). "However, emerging reports indicate that SRCAP may play a role in cancer initiation and progression, but additional research is needed as even its status as a tumor suppressor or oncogene remains unclear." (PMID 40858549, 2025). "Our results that five epidriver candidates (SRCAP, EP400, ARID1B, MBD5, and KMT2A) among the top 15 ERGs enriched in EMT fraction were found among the most mutated ERGs in clinical samples across cancer types support the driver role of EMT-specific ERG tumorigenesis." (PMID 32963031, 2020). "In contrast, the mRNA level of GRP78, which is usually over-expressed in cancer cells and has enriched H2A.Z around its promoter, was not reduced and even modestly increased after SRCAP knockdown." (PMID 22479200, 2012).